BDNF (brain derived neurotrophic factor)
Diseases named in the same sentence as BDNF in open-access papers (continued):
Sharing a sentence is not in itself a finding about the gene and the disease.
depression (continued). "Depression has also been conceptualized as a neurodevelopmental disease, and some neuroplasticity entities such as brain-derived neurotrophic factor (BDNF) deficiency may play a crucial role in its pathophysiology." (PMID 35409544, 2022). "Since oxidative stress was proposed as one of the causes of depression, and because lower levels of BDNF are linked to emotional despair, Hacioglu and collaborators studied the neuroprotective effect of BDNF on stress-induced oxidative damage in transgenic male mouse models." (PMID 36499240, 2022). "Furthermore, after controlling for gender and age, the assays showed lower serum BDNF levels being associated with higher depression scores." (PMID 35836661, 2022). "In this regard, it has been hypothesised that the increase in BDNF caused by the practice of physical activity could partially be implied from a decrease in the hippocampal atrophy, therefore, protecting against depression." (PMID 35206257, 2022). "Animal models of stress and depression-like behavior have revealed decreased BDNF expression, as well as loss of synaptic plasticity, particularly in the hippocampus, as well as restoration of BDNF expression with extended antidepressant treatment." (PMID 36467104, 2022). "Indeed, accumulating evidence indicates significant associations between reduced BDNF levels and depression and strong BDNF-mediated anti-depressant actions." (PMID 35955546, 2022). "Additionally, it was already observed that BDNF rs6265 polymorphism increases the risk for depression." (PMID 35955088, 2022). "Interestingly, we report a gene-environment interaction effect in which Met allele carriers of the BDNF Val66Met polymorphism who reported more hours of physical activity showed a decreased prevalence of depression." (PMID 35206257, 2022). "Depression is known to correlate with decreased serum brain-derived neurotrophic factor (BDNF), which is in turn associated with poorer stroke recovery, and may constitute a primary mechanism of this interaction." (PMID 36468065, 2022). "In this study of older adults with and without HIV, the authors found that plasma concentrations of brain-derived neurotrophic factor (BDNF) were significantly associated with depression, such that lower levels of plasma BDNF were linked to higher levels of depressive symptoms." (PMID 35618889, 2022). "Interestingly, the association between plasma BDNF and frailty remained even after exclusion of the effects of dementia, depression, and metabolic disorders, including stroke, diabetes, CVD, and osteoporosis." (PMID 36329115, 2022). "Interestingly, reduced BDNF levels were linked to depression, and a major mode of action of antidepressant drugs was recently revealed to be the amplification of BDNF-Trkb-signaling." (PMID 36232412, 2022). "Chronic oral corticosterone (CORT) induced increased anxiety- and depression-like behavior in wild-type male mice and male mice heterozygous for the gene coding for brain-derived neurotrophic factor Val66Met, a variant associated with genetic susceptibility to stress." (PMID 34848858, 2022). "Thus, a decrease or increase in BDNF levels appears to be associated with depression during adolescence." (PMID 35875661, 2022). "Moreover, the therapeutic effects of paroxetine therapy are associated with polymorphism of the BDNF gene, whereby carriers of the A allele of BDNF G196A polymorphism respond better to the paroxetine therapy in AD-related depression." (PMID 35090576, 2022). "Furthermore, the reduced level of BDNF has been associated with anhedonia which is the main symptom of depression." (PMID 35711916, 2022).
depression (continued). "Also, BDNF has been found to be associated with brain and psychological disorders such as memory dysfunction, depression, and anxiety." (PMID 36232200, 2022). "Perturbed BDNF expression has therefore been linked to depressive disorders." (PMID 35909451, 2022). "In addition, BDNF is a crucial brain signaling protein associated with depression disorder that plays a vital role in neuronal plasticity." (PMID 35873590, 2022). "Lower BDNF secretion in depressed patients may partly underlie the pathological mechanism of depression." (PMID 34300001, 2021). "In addition, we also observed association between depression severity and reduced positive affect with decreased promoter IV methylation, which was previously shown to correlate negatively with BDNF expression." (PMID 34325733, 2021). "Besides the BDNF-TrkB pathway, several genes have been associated with depression, and most are related to the hypothalamic-pituitary-adrenal (HPA) axis, or 5-HT/dopamine reuptake." (PMID 34959450, 2021). "BDNF has in fact an important role in the maintenance and survival of neurons and in synaptic plasticity and an abnormal neural plasticity is often associated with depression." (PMID 34638592, 2021). "Interestingly, late-life depression was also associated with elevated BDNF methylation of specific CpG sites within BDNF promoters I and IV." (PMID 33643008, 2021). "A cross-sectional study demonstrated that the Met allele of the BDNF gene might interact with two short alleles in the promoter region of the 5-HTTLPR increasing the risk for depression in maltreated children." (PMID 33643008, 2021). "BDNF conditional overexpression mice were observed to be less susceptible to depression." (PMID 34249519, 2021). "Moreover, low serum BDNF has been found to be associated with suicidal ideation in major depressive disorder." (PMID 34526917, 2021). "Collectively, abnormalities in Nrf2 and BDNF crosstalk in the brain may play a role in causing depression-like phenotypes in rodents." (PMID 33627628, 2021). "The BDNF hypothesis postulates that the loss of BDNF plays a major role in the pathophysiology of depression." (PMID 34576215, 2021). "The BDNF Val66Met polymorphism can alter the association between stroke and depression." (PMID 34759285, 2021). "Rapid and transient upregulation of BDNF reversed or blocked atrophy and cell loss in patients with depression, and it may be a critical component in subanesthetic intravenous ketamine’s antidepressant actions." (PMID 33850645, 2021). "Other BDNF gene variants, such as rs908867 and rs925946 in depression, and rs7103411, rs988748, and rs7130131 associated with long-term visual memory in healthy controls, might also affect cognition and were not assessed." (PMID 33926045, 2021). "Chronic exposure to NP at environmental doses will result in the accumulation of NP in the brain and blood, and induction of depression, which might be associated with the alterations in the expression levels of BDNF and monoamine neurotransmitters." (PMID 34046258, 2021). "Finally, the association between depression and BDNF gene profiles is much more evident in those studies using in-person interviews or objective measures to assess stress (e.g., trained investigators) than in studies using self-report methods." (PMID 33643008, 2021). "Interestingly, a point mutation in the human BDNF gene is associated with depression and bipolar disorder." (PMID 34276318, 2021). "Depression scores based on validated clinical scales and certain biomarkers associated with depression including cortisol, proinflammatory cytokines and brain-derived neurotrophic factor (BDNF) levels were used to demonstrate the anti-depressive effect of probiotic intervention." (PMID 34065187, 2021). "The BDNF hypothesis of depression postulates that a loss of BDNF is directly involved in the pathophysiology of depression and that its restoration may underlie the therapeutic efficacy of antidepressant treatments." (PMID 34884465, 2021).
depression (continued). "In addition to PPARα, there are a lot of other proteins that not only control BDNF biosynthesis and neuroplasticity but also are implicated in depression, such as salt-inducible kinase 2, glycogen synthase kinase 3β and mammalian target of rapamycin." (PMID 34211395, 2021). "Indeed, a study has suggested that the serotonin (5-HT)–BDNF systems act synergistically on synaptic plasticity and neurogenesis in brain areas implicated in depression." (PMID 33643008, 2021). "Furthermore, in a large representative sample of older American veterans, the BDNF Val66Met polymorphism moderated the association between depression and lower cognitive performance." (PMID 33643008, 2021). "The depression ameliorating effects of BoNT/A was associated with increased expression levels of 5‐hydroxytryptamine and brain‐derived neurotrophic factor (BDNF) in mice brain and BDNF/extracellular signal regulated kinase(ERK)/cyclic AMP response element (CRE)‐binding protein (CREB) pathways." (PMID 34423572, 2021). "The glutamatergic theory of depression is also associated with the participation of the BDNF." (PMID 34300299, 2021). "In addition, the inhibitory effect of Pdcd4 on BDNF mRNA translation depends on eIF4A, which extends our understanding of the mechanisms underlying the vital role of mRNA translation in depression regulation." (PMID 32203159, 2021). "First, PAI-1 may contribute to the cleavage of pro-brain-derived neurotrophic factor (BDNF) into its mature form, and BDNF is strongly implicated in depression." (PMID 35126596, 2021). "Thus, the results of human and animal experiments were consistent, demonstrating that a reduction in the BDNF level is one possible mechanism for NP causing depression-like behavioral changes." (PMID 34046258, 2021). "Studies have shown that BDNF is associated with depression in animal models." (PMID 34207545, 2021). "Additionally, Spearman’s correlation revealed a significant association between BDNF (ng/mL), handgrip (kgf), Beck depression inventory, and both dimensions of emotional role and emotional well-being." (PMID 34769814, 2021). "Alteration to BDNF expression is associated with major depressive disorder." (PMID 32203159, 2021). "We speculate that our findings are consistent with research indicating that the Met allele is a vulnerability allele for depression (and mental disease in general) due to its impairing effect on BDNF translocation and secretion." (PMID 34325733, 2021). "Thus, the contribution of BDNF to prevention of late-onset depression, which is directly associated with the etiology of AD, can be highlighted." (PMID 34161531, 2021). "Further, increased neurotransmitter glutamate is associated with an increase in the production of kynurenic and quinolinic acids and may result in reduced brain-derived neurotrophic factor that is widely associated with depression." (PMID 34112126, 2021). "Previous studies demonstrated that a reduction in brain BDNF levels may predict major depressive disorder, while an increase in brain BDNF levels is associated with antidepressant effects." (PMID 33954123, 2021). "In conclusion, we examined the hypothesis that the BDNF-TrkB signaling pathway is impaired and causes the elevation of depression-like behavior in mTBI-J treated rats." (PMID 34959450, 2021). "The downregulation of BDNF caused by reduced Nrf2 activity may play a key role in depression-like phenotypes in rodents." (PMID 33627628, 2021). "Preclinical studies suggested that BDNF/TrkB signaling may be involved in the underlyingmechanisms of depression- and anxiety-like behaviors in Ps mice models." (PMID 34819201, 2021). "Additionally, lower plasma BDNF level was found to be associated with suicidal behaviour in major depressive disorder." (PMID 34876186, 2021). "Additionally, it was reported that BDNF-Val66Met-polymorphism interacts with tDCS dose to predict neurocognitive outcomes in patients with depression." (PMID 34069556, 2021).
depression (continued). "In conclusion, we demonstrate that hippocampal GPAT4 might participate in HFD induced depression by activating AMPK, CREB and BDNF pathways, which provides insights into a clinical target for obesity-associated depression intervention." (PMID 34054732, 2021). "We asked whether maternal depression and/or anxiety during pregnancy were associated with altered serum BDNF levels in mothers (n = 251) and their new-born infants (n = 212)." (PMID 33462179, 2021). "However, the presence of the BDNF Val66Met polymorphism was associated with geriatric depression in a previous meta-analysis of studies of late-life depression with low level of heterogeneity and publication bias." (PMID 33643008, 2021). "We would like to introduce a clinical study examining a BDNF polymorphism (Val66Met) in depression." (PMID 34577589, 2021). "Observations that antidepressants induce the expression of BDNF in rodents and depressed patients led to the hypothesis that depression is associated with lower levels of BDNF and antidepressants act by restoring its levels." (PMID 33941769, 2021). "We evaluated mature BDNF (mBDNF), S100B levels in plasma and their associations with depression severity in 30 Selective Serotonin Reuptake Inhibitor (SSRI)-resistant MDD patients enrolled in a randomized controlled trial of ketamine compared (n = 20) to a placebo (n = 10) control (saline)." (PMID 34354565, 2021). "A number of studies have shown that BDNF is profoundly implicated in depression." (PMID 34776888, 2021). "At present, the role of miRNAs associated with GABA release and BDNF expression in depressive disorders remain unclear." (PMID 34674715, 2021). "Cumulative evidence has revealed that certain immunologic biomarkers including brain-derived neurotrophic factor (BDNF) and cytokines, gastrointestinal biomarkers, hormones, oxidative stress, and certain hypothalamus-pituitary axis biomarkers are associated with depressive disorder." (PMID 34576215, 2021). "BDNF expression changes are associated with severe depressive disorder." (PMID 33960267, 2021). "BDNF interacts with several neurotransmitters, including serotonergic, glutamatergic, and GABAergic neurotransmission that are implicated in the underlying mechanisms of depressive disorders." (PMID 34141514, 2021). "Although BDNF is primarily produced by the brain and has an influence on the growth and survival of neurons, it may be associated with depression." (PMID 32265693, 2020). "However, contradictory results regarding the relationship between BDNF, BDNF genotype polymorphisms and depression exist." (PMID 32372985, 2020). "Overall, BDNF is one of the key molecules modulating and linking brain plasticity, and the neuroplasticity hypothesis postulates that the loss of BDNF plays a major role in the pathophysiology of poststroke depression and depression with AD." (PMID 33029119, 2020). "Furthermore, and despite the gender by age interaction on prolactin, we did not observe a similar gender or age modification of the genetic association with either depression status or prolactin/BDNF." (PMID 32116853, 2020). "Single nucleotide polymorphisms (SNPs) in the BDNF gene may be one of the important factors leading to brain dysfunction, which can lead to depression." (PMID 32351365, 2020). "BDNF deficiency has been associated with age-dependent impairment in spatial learning, neurodegeneration, and cognitive dysfunction, as well as with depression." (PMID 32629761, 2020). "The protective effect of BDNF on depression is also associated with monoamine neurotransmitters." (PMID 31941442, 2020). "Some studies have reported that depression caused by chronic stress disrupts the BDNF–tropomyosin related kinase B (TrkB) receptor signaling pathway in the PFC and hippocampus, and ultimately contributes to impaired synaptic maturation, synaptic protein synthesis, and glutamate receptor cycling." (PMID 32922295, 2020).
depression (continued). "The neurotrophic hypothesis of depression posits that depression should be associated with decreased BDNF expression, potentially driven by BDNF hypermethylation." (PMID 32012861, 2020). "Another SNP, BDNF Val66Met, by way of affecting the expression of miR-146b, induced increases in the levels of Per1 mRNA, Npas4 mRNA, and Irak1 proteins, which have been associated with greater risk for depression." (PMID 33575257, 2020). "Decreased BDNF levels in brain have been associated with clinical depression, PD, and AD." (PMID 33233734, 2020). "Specifically, changes in BDNF promoter IV methylation levels are implicated in depression." (PMID 33096634, 2020). "Finally, we generated mice with conditional BDNF deletion in the mPFC and determined the impact of BDNF loss on depression-related behaviors and FoxO1 expression in mPFC." (PMID 32532322, 2020). "Studies have found that the pathogenesis of depression and the mechanisms underlying antidepressant therapeutic action are related to the tissue plasminogen activator (tPA)/brain-derived neurotrophic factor (BDNF) lysis pathway." (PMID 32153441, 2020). "Depression is associated with both decreased levels of BDNF and PSA-NCAM levels." (PMID 32372985, 2020). "Moreover, there are neuroplastic effects of mature BDNF that are also affected, which are suggested to be associated with several diseases, including major depression, anxiety, and hypothalamus–pituitary–adrenal-axis activity." (PMID 32859253, 2020). "Nevertheless, we observed a significant association between BDNF rs6265 and the severity of depression, which might mean that this reflects a relatively robust effect." (PMID 32116853, 2020). "Finally, a recent paper showed that subjects with the Met allele of the BDNF gene are more likely to develop depression." (PMID 33096634, 2020). "The high level of cortisol causes atrophy and decreasessynaptic density in the hippocampus, effectively decreasing the neurotransmitterrelease regulated by BDNF, eventually leading to disorders in learning, memory, andother cognitive functions, besides causing depression." (PMID 32206197, 2020). "The 1990s witnessed the rise of the “neurotrophic” hypothesis of depression, which associated chronic stress and depression with a deficit in BDNF and demonstrated that traditional antidepressants increased BDNF expression." (PMID 33329109, 2020). "Grassi-Oliveira and colleagues found an association between decreased levels of plasma BDNF and childhood-neglect-induced depression and memory impairment, which lends support to the possible wide impacts of the social psychological stressor and is worthy of further study." (PMID 32085670, 2020). "Furthermore, the presence of M1 polarized microglia, the proinflammatory microglial cell, is associated with low BDNF brain levels in an LPS-induced depression-like model." (PMID 32015787, 2020). "The common pathologies associated with AD, PD, and depression include neuroinflammation, oxidative stress, mitochondrial dysfunction, and reduction of neurotrophic factors such as brain-derived neurotrophic factor (BDNF)." (PMID 32867357, 2020). "Furthermore, recent studies reported an increased BDNF methylation is associated with depression in animal models and in humans." (PMID 32942585, 2020). "Further, elevated spinal growth factors, especially BDNF, are pronociceptive after nerve injury, and low levels of they in the supraspinal areas (like hippocampus) are associated with stress, depression, and pain." (PMID 34589875, 2020). "Although the structural and functional changes implicated in the relationship between depression and neurodegeneration seem to be highly complex, excitingly, several studies have shown altered BDNF production and secretion in a variety of neurodegenerative diseases as well as in depression." (PMID 33029119, 2020).